HADH (hydroxyacyl-CoA dehydrogenase)
Description:
Mitochondrial fatty acid beta-oxidation enzyme that catalyzes the third step of the beta-oxidation cycle for medium and short-chain 3-hydroxy fatty acyl-CoAs (C4 to C10). Plays a role in the control of insulin secretion by inhibiting the activation of glutamate dehydrogenase 1 (GLUD1), an enzyme that has an important role in regulating amino acid-induced insulin secretion (By similarity). Plays a role in the maintenance of normal spermatogenesis through the reduction of fatty acid accumulation in the testes (By similarity).
Synonyms: HCDH; HAD; HADHSC; SCHAD; HADH1; HHF4; MSCHAD
Tractability: Small molecule: a structure with a bound ligand is known; it has a high-quality binding pocket. PROTAC: ubiquitination databases record sites on it; its protein half-life has been measured.
Target class: Enzyme; Oxidoreductase
Gene: Protein-coding gene on chromosome 4 (107,989,714 to 108,035,241, forward strand). Ensembl gene ENSG00000138796.
Subcellular location: Mitochondrion matrix
Subcellular location (Human Protein Atlas): Mitochondria
Pathways (Reactome):
Metabolism: Beta oxidation of butanoyl-CoA to acetyl-CoA; Beta oxidation of decanoyl-CoA to octanoyl-CoA-CoA; Beta oxidation of hexanoyl-CoA to butanoyl-CoA; Beta oxidation of lauroyl-CoA to decanoyl-CoA-CoA; Beta oxidation of octanoyl-CoA to hexanoyl-CoA
Metabolism of proteins: Mitochondrial protein degradation
Gene Ontology:
Molecular function: (3S)-3-hydroxyacyl-CoA dehydrogenase (NAD+) activity; identical protein binding; NAD+ binding; long-chain (3S)-3-hydroxyacyl-CoA dehydrogenase (NAD+) activity; oxidoreductase activity; oxidoreductase activity, acting on the CH-OH group of donors, NAD or NADP as acceptor
Biological process: fatty acid beta-oxidation; positive regulation of cold-induced thermogenesis; regulation of insulin secretion; fatty acid metabolic process; negative regulation of insulin secretion; response to activity; response to hormone; response to insulin; response to xenobiotic stimulus
Cellular component: cytoplasm; mitochondrion; mitochondrial matrix
Genetic constraint (gnomAD): Loss-of-function variants: 10 observed, 15.56 expected, observed/expected ratio (o/e) 0.64, 90% interval 0.4 to 1.09. The upper end of that interval is the gene's LOEUF score, 1.09, which puts it in group 4 of 6, group 1 being the genes least tolerant of losing a copy. Missense variants: 190 observed, 235.48 expected, observed/expected ratio (o/e) 0.81, 90% interval 0.72 to 0.91. Synonymous variants: 91 observed, 94.38 expected, observed/expected ratio (o/e) 0.96, 90% interval 0.81 to 1.15.
Homologues: Orthologues: chimpanzee HADH (99% identical), macaque HADH (97% identical), pig HADH (93% identical), rat Hadh (90% identical), mouse Hadh (90% identical), guinea pig HADH (89% identical), tropical clawed frog hadh (77% identical), zebrafish hadh (75% identical), dog HADH (73% identical), rabbit HADH (72% identical), Caenorhabditis elegans ech-8 (26% identical), Caenorhabditis elegans ech-9 (24% identical). Paralogues in human: HADHA (32% identical), EHHADH (30% identical), CRYL1 (22% identical).
Diseases named in the same sentence as HADH in open-access papers:
HADH is named in the same sentence as 54 diseases in open-access papers, as found by Europe PMC text mining. Sharing a sentence is not in itself a finding about the gene and the disease. The quoted sentences say what the papers report.
hyperinsulinism (12 papers, 2013 to 2024). Abnormally high levels of insulin in the blood. "HADH is reported as a common cause of hyperinsulinemia and the function of HADH needs further to determine in central precocious puberty." (PMID 34748517, 2021). "Unlike other congenital fatty acid oxidation defects, short-chain L-3-hydroxyacyl-CoA (SCHAD, HADH) deficiency is characterised by hypoglycemia with hyperinsulinism in the neonatal or infancy periods." (PMID 26316438, 2015). "A loss-of-function mutation in the HADH gene was associated with fasting hyperinsulinemia." (PMID 31929791, 2019). "HADH mutations are a rare cause of recessively inherited congenital hyperinsulinism." (PMID 26740944, 2015). "The sequencing of the hydroxyacyl-coenzyme A dehydrogenase (HADH) gene was normal, thus excluding short-chain 3-hydroxyacyl-coenzyme A dehydrogenase hyperinsulinism (SCHAD-HI)." (PMID 38279270, 2024). "In addition, site cg27527503 is in the promoter region of the HADH gene, which is differentially expressed with respect to diabetes status and is a primary driver of hyperinsulinism and hyperinsulinaemic hypoglycemia." (PMID 37934796, 2023).
diabetes (10 papers, 2010 to 2025). "Specifically in β-cells, TG-induced stress resulted in increased expression of ARID5B (part of demethylase complex), MAP1LC3A (Mitophagy), and CLIC1 (chloride channel) expression and decreased G6PC2 and HADH, which have been associated with diabetes." (PMID 38956087, 2024). "For PGRMC1 and HADH, their associations ranked at the top 5% (i.e., U-score ≤ 0.05) in the six diabetes studies and their best U-scores were 0.34% and 0.44% in the diabetes studies 9 and 11 of the pancreas, respectively." (PMID 28117714, 2017). "A gene expression meta-analysis also revealed the existence of possible pleiotropic mechanisms manifest via common gene signatures (PGRMC1 and HADH) across different diabetes phenotypes." (PMID 35788821, 2022). "Our analysis showed that PGRMC1 and HADH genes were significant over diabetes studies, while IRS1 and MPST genes were significant over insulin response studies, and joint analysis showed that HADH and MPST genes were significant over all combined data sets." (PMID 28117714, 2017). "HADH is an enzyme involved in β‐oxidation of fatty acids that is enriched in cardiomyocytes, and possibly involved in endothelial dysfunction in patients with diabetes." (PMID 40891821, 2025). "In addition to NKX6–1 we found variants in WFS1, RFX6 and 7 other genes associated with monogenic forms of diabetes (AKT2, EIF2AK3, GLIS3, HADH, MNX1, NKX2–2, and PTF1A) and they may be relevant to development of MODY." (PMID 29439679, 2018). "Although an association between diabetes and common specific variants in this gene has not been demonstrated, altered HADH expression has been described in diabetes." (PMID 35246208, 2022). "Our meta-analysis showed that PGRMC1, HADH, IRS1 and MPST were the four tissue non-specific genes presenting differential expression association with the diabetes or insulin response." (PMID 28117714, 2017). "The HADH was significant in six diabetes studies (studies 1, 3, 5, 8, 11 and 13) of adipose, blood, EPC, myotube, pancreas and skeletal muscles, and the gene had the smallest U-score of 0.44% at the study 11 of pancreas that compared T2D with non-diabetes." (PMID 28117714, 2017). "By comparing the direct overlap between the heterogeneous islet diabetes-related gene sets we identified genes such as ANPEP and HADH that are currently not well-established as diabetes susceptibility genes but had consensus support across evidence sources." (PMID 28473845, 2017).
gastric cancer (8 papers, 2017 to 2025). A primary or metastatic malignant neoplasm involving the stomach. "Knockdown of HADH significantly promoted gastric cancer cell migration and invasion, which was associated with increased expression of p-Akt." (PMID 29100311, 2017). "Additionally, similarly to gastric cancer, HADH downregulation was significantly associated with poor OS, DFS, and poor prognosis in kidney renal clear cell carcinoma." (PMID 36313354, 2022). "Previous study illustrated that the reduction of HADH-mediated gastric cancer showed a deceleration of β-oxidation that leads to the accumulation of fatty acids, activating the PI3K-Akt signaling pathway, which often promotes malignant tumor growth." (PMID 39762212, 2025). "Similar to gastric cancer tissues, HADH expression was markedly downregulated in kidney renal clear cell carcinoma tissues compared with that in adjacent non-cancerous tissues." (PMID 36313354, 2022). "HADH is expressed at lower levels in gastric cancer tissues compared with that in normal gastric tissues." (PMID 36313354, 2022). "HADH expression is upregulated or downregulated in different types of cancers, including gastric cancer, kidney renal clear cell carcinoma, liver cancer, colon cancer, and acute myeloid leukemia." (PMID 36313354, 2022). "In summary, HADH is a potential novel tumor suppressor gene in gastric cancer that can inhibit cell proliferation, migration, and invasion of gastric cancer cells." (PMID 36313354, 2022). "illustrated that the downregulation of HADH facilitated gastric cancer cell migration and invasion through activating the Akt signaling pathway, associated with more advanced stage and poorer outcomes." (PMID 35250999, 2022). "After the downregulation of HADH, β-oxidation was inhibited in gastric cancer cells, which led to the accumulation of fatty acids." (PMID 33688464, 2021). "Taken together, these data suggest that the downregulation of HADH promotes gastric cancer progression through the activation of Akt signaling pathway.Because Akt is negatively regulated by PTEN, the expression of PTEN was detected by qPCR and Western blot." (PMID 29100311, 2017). "Knockdown of HADH promoted the proliferation, migration and invasion of the gastric cancer cells MKN45 via activation of Akt signaling pathway." (PMID 29100311, 2017). "In conclusion, our study demonstrates that the expression of HADH is decreased during gastric cancer progression." (PMID 29100311, 2017). "We also examined the role of HADH in gastric cancer cell migration and invasion using a transwell system and identified the signaling pathways mediating HADH's effect." (PMID 29100311, 2017). "By contrast, HADH over expression inhibit growth of gastric cancer cells compared to cells transfected with empty plasmid." (PMID 29100311, 2017). "Herein, for the first time, we demonstrate that downregulation of HADH promotes gastric cancer progression via activation of Akt signaling pathway." (PMID 29100311, 2017). "To determine the significance of HADH downregulation in gastric cancer progression, we tested the impact of HADH knockdown or overexpression on the migration and invasion of the gastric cancer cells using a transwell assay." (PMID 29100311, 2017). "HADH knockdown or overexpression was achieved by transfecting MKN45 gastric cancer cells with shRNA or plasmid carrying full length human HADH cDNA, respectively." (PMID 29100311, 2017). "Western blot analysis revealed that HADH was decreased in stage I/II gastric cancer samples compared to matched adjacent normal gastric tissue, and its expression was further decreased in stage III/IV samples." (PMID 29100311, 2017). "The specific functions and molecular details of HADH in the incidence and progression of various cancers are summarized in this article, with an emphasis on gastric cancer, kidney renal clear cell carcinoma, liver cancer, colon cancer, and acute myeloid leukemia." (PMID 36313354, 2022).
gastric cancer (continued). "By contrast, HADH overexpression inhibited the migration and invasion of these cells.We thenperformed these experiments using two additional gastric cancer lines AGS and N87 cells and the data confirmed that HADH knockdown promotes gastric cancer cell invasion and migration." (PMID 29100311, 2017). "Because we have shown HADH down regulation correlates tumor progression in most of the GC samples, we then investigated whether HADH knockdown or overexpression affects gastric cancer cell proliferation in vitro." (PMID 29100311, 2017). "The aim of this study was to identify the role of HADH in gastric cancer." (PMID 29100311, 2017). "We analyzed the expression of HADH in 102 pairs of gastric cancer samples." (PMID 29100311, 2017). "However, the role of HADH in gastric cancer progression remains unknown." (PMID 29100311, 2017). "We analyzed HADH basal expression level in N87, AGS and MKN45 gastric cancer lines and our results showed similar moderate HADH expression in all three cell lines." (PMID 29100311, 2017). "HADH expression is reduced in gastric cancer, where it inhibits PTEN expression and promotes AKT phosphorylation, thereby activating the Akt signaling pathway and facilitating gastric cancer cell migration and invasion." (PMID 41583431, 2025).
acute myeloid leukemia (4 papers, 2022 to 2024). Acute myeloid leukemia (AML) is a group of neoplasms arising from precursor cells committed to the myeloid cell-line differentiation. "Research indicates that elevated HADH expression is correlated with an unfavorable prognosis in acute myeloid leukemia patients." (PMID 38649912, 2024). "For example, several studies have demonstrated that the overexpression of HADH was related to poor clinical outcomes in acute myeloid leukemia and colon cancer." (PMID 35250999, 2022). "Similar to colon cancer tissues, HADH expression was markedly upregulated in acute myeloid leukemia patient samples." (PMID 36313354, 2022). "However, the precise molecular mechanism by which HADH acts in acute myeloid leukemia is unknown, and more research is needed." (PMID 36313354, 2022).
breast carcinoma (4 papers, 2017 to 2026). "In the ieu-a-1126 cohort, genes with causal relationships to breast cancer included GNB2, HADH, OAS2, OCIAD2, P4HA2, and PAFAH1B3." (PMID 41424847, 2026). "Therefore, HADH might have a similar function in the development of breast cancer." (PMID 31208363, 2019). "The expression of hydroxyacyl-CoA dehydrogenase was significantly under-expressed in breast cancer; especially in those with estrogen receptor-negative status and those with metastatic and recurring breast cancers." (PMID 29100311, 2017).
colon cancer (4 papers, 2018 to 2024). "High HADH levels can promote colon cancer cell proliferation and are significantly associated with poor clinical outcomes." (PMID 36313354, 2022). "Wnt5a/b has been demonstrated to regulate HADH expression, with HADH relying on Evi/Wls secretion to act on the β-catenin-independent Wnt signaling pathway for regulation of colon cancer cell growth and proliferation." (PMID 36313354, 2022). "In colon cancer cells, the Wnt signaling pathway is required for HADH-mediated regulation of cell proliferation." (PMID 36313354, 2022). "Poor clinical outcomes have also been observed in colon cancer patients with high HADH expression." (PMID 38649912, 2024). "Thus, HADH potentially functions as an oncogene in colon cancer." (PMID 36313354, 2022). "In HT29 colon cancer cells, mRNA expression of PLOD2, HADH and LCOR as well as AXIN2 as a canonical control target was downregulated upon treatment with the Porcupine inhibitor LGK974." (PMID 29453334, 2018). "Unlike gastric, kidney, and liver cancers, HADH is highly expressed in colon cancer cells." (PMID 36313354, 2022). "Independent experiments confirmed several target genes, including PLOD2, HADH, LCOR and REEP1 as non-canonical target genes in various colon cancer cells." (PMID 29453334, 2018). "Taken together, these experiments confirmed PLOD2, HADH, and LCOR as non-canonical Wnt targets that depend on Wnt secretion but not on β-catenin in colon cancer cell lines as well as primary colon cancer cells and MEFs." (PMID 29453334, 2018). "Silencing of ATF2 revealed downregulation of PLOD2, HADH, LCOR and REEP1 mRNA expression; thus suggesting ATF2 as the transcription factor in non-canonical Wnt signaling in colon cancer cells." (PMID 29453334, 2018).
MODY (4 papers, 2018 to 2024). "HADH expression was significantly (p < 0.044) lower in patients with suspected MODY versus controls." (PMID 35246208, 2022). "This was expected since for this gene, in the initial comparison between groups, we already detected that HADH had significantly lower expression in MODY than in controls." (PMID 35246208, 2022). "Other rare variants found in a South Indian population that could potentially play a role in MODY pathogenesis are EIF2AK3, GLIS3, HADH, and PTF1A." (PMID 39201476, 2024).
Obesity (4 papers, 2019 to 2026). Accumulation of substantial excess body fat. "HADH is also related to the development of obesity and lipid metabolism." (PMID 31929791, 2019). "In this study, IPA eased the identification of obesity markers, and we chose ASCL1, HADH, and UCHL1 for validation based on both our proteomic analysis and previous research." (PMID 31929791, 2019). "Similarly, reduced ACADSB and HADH mRNA levels were also correlated with increased hip circumference, suggesting that in the SAT, BCAA catabolic enzymes are downregulated in the setting of obesity." (PMID 32903728, 2020).
colorectal cancer (3 papers, 2017 to 2025). A primary or metastatic malignant neoplasm that affects the colon or rectum. "In colorectal cancer, HADH has been implicated in non-canonical Wnt signaling, regulating tumor proliferation and metabolic activity via the Wnt5a/b-Ror2/Dvl2-ATF2/4 axis." (PMID 40821775, 2025). "Interestingly, the decreased expression levels of ACADM, GSR and HADH were closely related to the deterioration of colorectal cancer patients (p < 0.01)." (PMID 36552870, 2022). "Moreover, HADH has been found to be extensively up-regulated in colorectal cancer cells, implying that fatty acid metabolism in HCT116 cells is excessively activated and fatty acid synthesis is important for colorectal cell proliferation." (PMID 28786914, 2017). "Therefore, we used the correlation of the expression level of genes with the prognosis of colorectal cancer patients as an evaluation index, and finally identified eight critical enzymes of amino acid metabolism in colon TAMs, namely, ACADM, ACADS, GPX4, GSR, HADH, HMGCL, HMGCS1 and IDH1." (PMID 36552870, 2022).
heart failure (3 papers, 2022 to 2025). Inability of the heart to pump blood at an adequate rate to meet tissue metabolic requirements. "Moreover, the detection of hydroxyacyl-CoA dehydrogenase subunits key enzymes involved in fatty acid β-oxidation further supported the hypothesis that impaired lipid metabolism is an early and detectable hallmark of heart failure progression." (PMID 41399465, 2025). "CS and HADH activity significantly declined only at the 4-week time point in hearts of both genotypes at a time when overt heart failure was present." (PMID 36125265, 2022).
Hypoglycemia (3 papers, 2015 to 2016). A decreased concentration of glucose in the blood. "Remarkably, hyperinsulinism and hypoglycemia are also caused by mutations in the short-chain 3-hydroxyacyl-CoA dehydrogenase (SCHAD), which is involved in the oxidation of fatty acids." (PMID 27983623, 2016). "The clinical presentation of CHH due to HADH mutations is heterogeneous with some patients presenting with severe neonatal hypoglycemia and others - with mild infancy-onset hypoglycemia." (PMID 26316438, 2015). "Eight (72 %) children with HADH mutation had a history of hypoglycemia following protein-rich meals, although no formal protein load test was done in these patients." (PMID 26268944, 2015).
Insulin resistance (3 papers, 2010 to 2024). Increased resistance towards insulin, that is, diminished effectiveness of insulin in reducing blood glucose levels. "The reduced activity of HADH may contribute to impaired BCAA oxidation, which has also been associated with the development of insulin resistance." (PMID 33667994, 2021).